RNU6-437P (RNA, U6 small nuclear 437, pseudogene)
Gene: Small nuclear RNA gene on chromosome 6 (107,930,088 to 107,930,182, forward strand). Ensembl gene ENSG00000238420.
Homologues: Orthologues: chimpanzee U6 (100% identical), macaque U6 (81% identical), mouse Gm26133 (71% identical), mouse Gm22476 (69% identical), guinea pig U6 (62% identical), rat LOC120099053 (59% identical), rabbit U6 (58% identical). Paralogues in human: RNU6-116P (80% identical), RNU6-144P (80% identical), RNU6-15P (80% identical), RNU6-16P (80% identical), RNU6-39P (80% identical), RNU6-502P (80% identical), RNU6-937P (80% identical), RNU6-1 (79% identical), RNU6-1031P (79% identical), RNU6-140P (79% identical), RNU6-196P (79% identical), RNU6-2 (79% identical), and 1284 more.